CYP24A1 (cytochrome P450 family 24 subfamily A member 1)
Diseases named in the same sentence as CYP24A1 in open-access papers (continued):
Sharing a sentence is not in itself a finding about the gene and the disease.
osteosarcoma (3 papers, 2020 to 2023). A usually aggressive malignant bone-forming mesenchymal neoplasm, predominantly affecting adolescents and young adults. "Calcipotriol treatment, on the other hand, not only increased the expression of CYP24A1 in MG63 osteosarcomas, but it also had a significant anti-tumor effect." (PMID 37228489, 2023). "In human osteosarcoma cells, after 24 h stimulation with 1,25(OH)D 100 nM we observed a significant upregulation of OCN, CDKN1A, CaBP9K and CYP24A1, which was blunted upon co-incubation with PFOA, with the exception of CaBP-9 K." (PMID 33033332, 2020).
rectal cancer (3 papers, 2019 to 2023). A primary or metastatic malignant neoplasm that affects the rectum. "According to the results of subgroup analysis of the cancer site, the hypermethylation of CYP24A1 was inversely associated with the risk of both colon and rectal cancer, with aORs of 0.18 (95% CI, 0.08–0.42; P < 0.001) and 0.20 (95% CI, 0.08–0.49; P < 0.001), respectively (Pheterogeneity = 0.86)." (PMID 37644572, 2023). "For rectal cancer, the interaction P-values of <0.05 were observed for CYP24A1 (vitamin D metabolism) and BMP2 (TGF signaling)." (PMID 31434255, 2019).
Renal insufficiency (3 papers, 2023 to 2025). A reduction in the level of performance of the kidneys in areas of function comprising the concentration of urine, removal of wastes, the maintenance of electrolyte balance, homeostasis of blood pressure, and calcium metabolism. "In our patient, as well as in the other 5 described patients with the CYP24A1 mutation and PHPT, mild renal failure was noted; however, the phosphate concentration remained low." (PMID 38665259, 2024).
Stroke (3 papers, 2020 to 2023). Sudden impairment of blood flow to a part of the brain due to occlusion or rupture of an artery to the brain. "Adali's research showed that CYP24A1 (rs927650) was associated with susceptibility of stroke with hypertensive, smoker, diabetic, and obese individuals." (PMID 31872978, 2020). "We observed that CYP24A1 rs2296241was associated with the increased stroke risk in males than in females." (PMID 31872978, 2020). "The results indicated that CYP24A1 rs1570669 was significantly association with stroke risk." (PMID 31872978, 2020). "However, there is very limited information about the polymorphism of the CYP24A1 gene association with stroke risk." (PMID 31872978, 2020). "Therefore, they believe that the single‐nucleotide polymorphisms (SNPs) in enzymes involved in vitamin D metabolism such as CYP24A1 gene is closely related to the occurrence of stroke." (PMID 31872978, 2020).
tuberculosis (3 papers, 2013 to 2022). A chronic, recurrent infection caused by the bacterium Mycobacterium tuberculosis. "The tuberculosis drug rifampin (also termed rifampicin) has also been successfully used to treat patients with pathogenic CYP24A1 mutations." (PMID 35745247, 2022).
alcoholism (2 papers, 2022 to 2023). "Smoking, alcohol consumption and DM stood out as independent factors for isolated cirrhosis; while for cirrhosis with HCC alcoholism, DM, age, male gender, presence of polymorphic allele of CYP24A1-rs6013897 (_/T), viral hepatitis and altered serum levels of GGT, AFP and creatinine were the factors." (PMID 35919232, 2022).
anaplastic thyroid cancer (2 papers, 2014 to 2022). "A study on anaplastic thyroid cancer cell lines showed that CYP24A1 knockdown led to the enhancement of vitamin D antitumor activity." (PMID 36362448, 2022).
chronic pancreatitis (2 papers, 2014 to 2023). A chronic inflammatory process causing damage and fibrosis of the pancreatic parenchyma. "Another human study showed that CYP24A1 of chronic pancreatitis tissues was primarily expressed in the endocrine islets, ducts, and acini." (PMID 37808100, 2023). "We show for the first time that the expression of the vitamin D degrading enzyme, CYP24A1 is increased both during inflammation (as in chronic pancreatitis) and during malignant transformation (as in pancreatic ductal adenocarcinoma)." (PMID 25090635, 2014). "In chronic pancreatitis patients the significant correlation of CYP24A1 and VDR suggests that high CYP24A1 expression in the islets is a physiological up-regulation of CYP24A1." (PMID 25090635, 2014). "Finally, this study did not compare acute and chronic pancreatitis, which might affect VDR, CYP24A1, and CYP27B1 expression levels." (PMID 37808100, 2023).
colorectal adenoma (2 papers, 2023 to 2025). An adenoma that arises from the colon or rectum. "Elevated CYP24A1 levels in colorectal adenomas and carcinomas correlate with proliferation markers and poor prognosis, and contribute to resistance to calcitriol-based therapies by promoting hormone inactivation." (PMID 41228419, 2025). "It was previously suggested that the overexpression of CYP24A1, i.e., inactivation of calcitriol, could be critical for progression of colorectal adenoma to carcinoma." (PMID 37242266, 2023). "In colorectal adenomas and carcinomas, CYP24A1 protein expression is elevated 2- to 4-fold compared to normal mucosa, and this correlates with proliferation markers (Ki-67) and reduced patient survival." (PMID 41228419, 2025).
diabetic nephropathy (2 papers, 2012 to 2023). "Previous studies have also shown that CYP24A1 (an enzyme implicated in vitamin D metabolism), might play an important role in furthering the progression of kidney lesions during diabetic nephropathy." (PMID 23119081, 2012). "We show that CYP24A1 expression was increased during diabetic nephropathy progression." (PMID 23119081, 2012).
differentiated thyroid carcinoma (2 papers, 2019 to 2020). Differentiated thyroid carcinoma (DTC), also known as papillary or follicular thyroid carcinoma, is a slow-growing malignancy usually presenting in adults as an asymptomatic thyroid mass. "Five hundred patients with differentiated thyroid cancer and 500 controls were genotyped for the DHCR7 rs12785878, CYP2R1 rs2060793, and CYP24A1 rs6013897 variants." (PMID 31357732, 2019).
ductal adenocarcinoma (2 papers, 2014 to 2019). "Similar to the consequences above, low CYP24A1 expression showed a close association with basal tumors, Lum A tumors, Lum B tumors, ER-negative tumors, ER-positive tumors, PR-negative tumors, PR-positive tumors, infiltrating ductal carcinoma and infiltrating lobular carcinoma." (PMID 31548577, 2019). "By comparing expression of the studied proteins in the various cell types of the pancreas, we are the first to show that during ductal adenocarcinoma development, the islet cells lose CYP24A1 expression while the transformed ductal cells up-regulate CYP24A1 expression." (PMID 25090635, 2014). "Further, our data suggest that during ductal adenocarcinoma development the vitamin D system in the pancreas becomes deregulated on two levels: In the islets CYP24A1 expression decreases weakening the negative feedback regulation of the vitamin D-dependent insulin synthesis and secretion." (PMID 25090635, 2014). "Our data suggest that during ductal adenocarcinoma development the vitamin D system in the pancreas becomes deregulated on two levels: in the islets CYP24A1 expression decreases weakening the negative feedback regulation of the vitamin D-dependent insulin synthesis/secretion." (PMID 25090635, 2014).
Esophageal Neoplasms (2 papers, 2014 to 2017). "The expression of CYP24A1 is increased in several malignancies, such as colon, ovary, breast, lung, and esophageal tumors." (PMID 25090635, 2014).
follicular adenoma (2 papers, 2014 to 2017). "Later, these findings were reproduced by other groups which reported that VDR, CYP27B1, and CYP24A1 expressions were increased in follicular adenoma and DTC, such as PTC and follicular thyroid cancer (FTC), when compared to normal thyroid tissue." (PMID 28895880, 2017). "When DTC was compared to follicular adenoma, significantly higher VDR and lower CYP24A1 expression was observed." (PMID 28895880, 2017).
gastric cancer (2 papers, 2021 to 2022). A primary or metastatic malignant neoplasm involving the stomach. "CYP2R1 rs12794714, CYP24A1 rs2762934, rs6068816, and VDR rs11574129 had been reported to be involved in the genetic background of multiple diseases including diabetic ischemic stroke, gastric cancer, and other diseases." (PMID 34925313, 2021).
idiopathic hypercalciuria (2 papers, 2017 to 2024). A rare renal disease characterized by persistent excess urinary calcium excretion in the absence of an underlying systemic disease and hypercalcemia. "Despite a vitamin D-mediated increase in intestinal calcium absorption in patients with low CYP24A1 activity, urinary calcium losses may prevail, and thus patients are overall in a negative calcium balance, as previously reported in patients with idiopathic hypercalciuria." (PMID 38765596, 2024).
inflammatory bowel disease (2 papers, 2025). A spectrum of small and large bowel inflammatory diseases of unknown etiology. "However, in diseases like inflammatory bowel disease (IBD), dysbiosis leads to elevated lipopolysaccharide (LPS) levels and increased cytokine production, disrupting the expression of key vitamin D hydroxylases, including CYP27B1 and CYP24A1." (PMID 41228419, 2025).
liver cirrhosis (2 papers, 2016 to 2023). "The expressions of 25(OH)-D3 and VDR decreased while that of 1,25-dihydroxyvitamin D 24-hydroxylase (CYP24A1) was increased in intestinal tissues of liver cirrhosis rats." (PMID 37273916, 2023). "We measured the levels of 25(OH)-VD3, VDR, and CYP24A1 in the ileum of rats and the serum of liver cirrhosis patients." (PMID 37273916, 2023). "The concentrations of 25(OH)-VD3 and VDR were remarkably attenuated in rat and human serum of liver cirrhosis, and in contrast, augmented levels of CYP24A1 were detected compared with the control group." (PMID 37273916, 2023). "Reduction in 25(OH)D3 levels is possibly due to downregulation of the synthetic hydroxylase CYP27A1 and concurrent upregulation of degrading CYP24A1 in patients with liver cirrhosis." (PMID 27399065, 2016). "Enzyme-linked immunosorbent and reverse transcription PCR (RT-PCR) analysis were used to determine the levels of 25(OH)-VD, vitamin D receptor, Cytochrome P450 24A1 (CYP24A1), and α-defensin 5 (DEFA5) in rat and human serum of liver cirrhosis." (PMID 37273916, 2023).
mineral metabolism disorders (2 papers, 2021 to 2025). "Two alleles associated with increased ALP, rs3923-T (SLC17A1 missense mutation) and rs764284-G (near CYP24A1), were associated with mineral metabolism disorders and intestinal malabsorption." (PMID 33547301, 2021).
Miscarriage (2 papers, 2024). A pregnancy that ends at a stage in which the fetus is incapable of surviving on its own, defined as the spontaneous loss of a fetus before the 22th week of pregnancy. "In a previous study, the placental and decidual expression of CYP24A1 was increased in patients with spontaneous miscarriage compared with that in healthy controls." (PMID 38791485, 2024).
myopia (2 papers, 2016 to 2022). "Genetic variants in the vitamin D pathway genes appeared not to be related: although SNPs in the VDR and CYP24A1 genes showed some association with AL and myopia, this did not remain after adjustment for multiple testing." (PMID 26955828, 2016).
oral squamous cell carcinoma (2 papers, 2020 to 2025). "Previous study indicated that ED-71 could suppress oral squamous cell carcinoma by inhibiting HBp17/FGFBP-1, FGF-2, CD31, Ki-67, and Cyp24A1." (PMID 33336024, 2020).
pancreatic ductal adenocarcinoma (2 papers, 2014 to 2023). An infiltrating adenocarcinoma that arises from the epithelial cells of the pancreas. "However, an increase in CYP24A1 expression in pancreatic tissue is associated with the development of pancreatic ductal adenocarcinoma in humans." (PMID 37808100, 2023).
papillary thyroid cancer (2 papers, 2011 to 2022). "In addition to increased expression of the vitamin D receptor (VDR) (responsible for mediating 1,25(OH)2D cellular actions) in papillary thyroid cancers, activity of the gene encoding CYP24A1 has also been found to be increased." (PMID 35807774, 2022). "Interestingly, a very recent study showed that that CYP24A1 expression is marked increased in papillary thyroid cancer (PTC) compared with normal thyroid tissues." (PMID 21988780, 2011).
prostate adenocarcinoma (2 papers, 2023 to 2025). "Previous studies have observed that the expression of CYP24A1 is partly regulated by DNA methylation in both lung and prostate adenocarcinomas." (PMID 39858498, 2025). "The expression of CYP24A1 was in part regulated by DNA methylation, which has been observed in both lung and prostate adenocarcinomas." (PMID 37644572, 2023).
Prostate tumor (2 papers, 2013 to 2014). "Prostate tumor derived endothelial cells (TDEC) expressed less CYP24A1 compared with endothelial cells derived from normal cells or matrigel plugs, which may be attributed to increased CYP24A1 promoter methylation in TDECs." (PMID 24808866, 2014).
renal carcinoma (2 papers, 2014 to 2022). A carcinoma arising from the epithelium of the renal parenchyma or the renal pelvis. "An increased level of CYP24A1 was observed in lung, ovarian, colon, esophageal and renal cancers." (PMID 25334067, 2014).
Sepsis (2 papers, 2022 to 2025). Sepsis is defined as life-threatening organ dysfunction caused by a dysregulated host response to infection. "Immunofluorescence results indicated that APS increased CYP27B1 protein expression and decreased CYP24A1 in rat kidneys, indicating that APS could effectively prevent renal cell apoptosis, reduce protein cast formation, and inhibit the occurrence of renal injury in rats with sepsis." (PMID 36338128, 2022).
skin melanoma (2 papers, 2014 to 2019). "Therefore, we analyzed CYP24A1 expression in relation to clinicopathomorphological features of nevi, skin melanomas and metastases." (PMID 25334067, 2014). "Also in skin melanoma, a significantly decrease in the expression of VDR, CYB27B1, CYP24A1, RORα and RORγ was observed in comparison to normal melanocytes or perilesional keratinocytes." (PMID 31235702, 2019).
type 1 diabetes (2 papers, 2020). "In conclusion, our data suggest a synergistic effect of multiple alleles at the DHCR7, GC, CYP2R1 and CYP24A1 loci on the susceptibility to type 1 diabetes, due to the role of these genes in the vitamin D pathway and their effect on serum vitamin D levels." (PMID 32764491, 2020). "Nevertheless, the combined number of DHCR7, GC, CYP2R1 and CYP24A1 minor alleles that each individual harboured was associated with the risk of type 1 diabetes in our population." (PMID 32764491, 2020). "The aim of this study was to evaluate whether the DHCR7 rs12785878, GC rs2282679, CYP2R1 rs2060793 and CYP24A1 rs6013897 SNPs are associated with the susceptibility to type 1 diabetes in the Portuguese population." (PMID 32764491, 2020).
Uterine leiomyoma (2 papers, 2020 to 2022). The presence of a leiomyoma of the uterus. "As observed herein, the lack of vitamin D3 catabolic enzyme in the porcine myometrium is inconsistent with currently available results for the human myometrium, showing a low level of CYP24A1 mRNA transcript abundance in normal myometrium and its overexpression in uterine leiomyoma." (PMID 35409330, 2022). "In this study, we have estimated the expression level of CYP24A1 hsa_circ_0060927 in uterine leiomyoma and adjacent tissues considering the mediator complex subunit 12 gene (MED12) mutation profile by quantitative real‐time polymerase chain reaction (qRT‐PCRs)." (PMID 31746073, 2020).
vitamin D metabolism disorders (2 papers, 2025). "Vitamin D 24-hydroxylase (CYP24A1) is an important enzyme in the regulation of vitamin D. To date, many different CYP24A1 mutations have already been described in the literature as causes of vitamin D metabolism disorders." (PMID 41009532, 2025).
Bartter syndrome (1 paper, 2025). "In our investigation, 28% of patients manifested genetic variants associated with calcium metabolism, encompassing mutations in CYP24A1, hereditary hypophosphatemic rickets, and Bartter syndrome." (PMID 40126616, 2025).
carcinomas in situ (1 paper, 2010). "In contrast, the expression of CYP24A1 is increased in carcinomas (56.0% in carcinomas in situ and 53.7% in invasive carcinomas) compared with the benign lesions (19.0%), which are mostly negative." (PMID 20831823, 2010). "The results obtained show that the three proteins (VDR, CYP27B1 and CYP24A1) display a statistically significant correlation of expression between the two sections (carcinomas in situ and the matching invasive tumour)." (PMID 20831823, 2010). "The main purpose of this work was to perform an immunohistochemical study of the expression of the VDR, CYP27B1 and CYP24A1 in a comprehensive series of human breast tissues comprised of normal breast, benign mammary lesions, carcinomas in situ and invasive breast carcinomas." (PMID 20831823, 2010). "The series of 189 tumours with both components (carcinomas in situ and the corresponding invasive tumour) allowed the evaluation of the expression of the VDR, CYP27B1 and CYP24A1 simultaneously in the two types of tumours." (PMID 20831823, 2010). "We have used a cohort comprising normal breast, benign mammary lesions, carcinomas in situ and invasive carcinomas and assessed the expression of the VDR, CYP27B1 and CYP24A1 by immunohistochemistry." (PMID 20831823, 2010).
celiac disease (1 paper, 2025). An autoimmune genetic disorder with an unknown pattern of inheritance that primarily affects the digestive tract. "Mechanistic summary: In celiac disease, inflammatory cytokines and epithelial injury induce CYP24A1 expression, increasing 1,25(OH)2D3 degradation and weakening mucosal immunity and barrier integrity, even in patients adhering to gluten-free diets." (PMID 41228419, 2025).
Cirrhosis (1 paper, 2022). A chronic disorder of the liver in which liver tissue becomes scarred and is partially replaced by regenerative nodules and fibrotic tissue resulting in loss of liver function. "CYP24A1-rs6013897 is associated with cirrhosis and HCC as a predictor, while DBP-rs4588 is associated with reduced vitamin D, and DBP-rs7041 provides increased survival, suggesting a protective characteristic." (PMID 35919232, 2022). "In this study, CYP24A1-rs6013897 (_/T) polymorphism was also associated with cirrhosis and HCC, as an independent factor for the disease, while the wild homozygous genotype (A/A) prevailed in controls." (PMID 35919232, 2022). "Thus, this study aimed at evaluating the association of genetic polymorphisms of DBP (rs4588 and rs7041) and CYP24A1 (rs6013897) in cirrhosis with or without HCC, considering demographic–clinical–biochemical profile, as well as lifestyle and survival habits." (PMID 35919232, 2022).
coronary artery calcification (1 paper, 2014). Calcification of the coronary artery, used as a measure of coronary atherosclerosis, a risk factor for myocardial infarction. "Lower 25(OH) vitamin D levels were an independent predictor of coronary artery calcification in an asymptomatic population and polymorphisms in the vitamin D regulatory gene CYP24A1 have been associated with coronary calcification in a cross-sectional analysis." (PMID 24586387, 2014).
depression (1 paper, 2023). "Rats exhibiting depression-like symptoms demonstrated increased expression of CYP27B1, CYP24A1 and VDR in the hippocampus and elevated levels of 1,25 (OH)2D." (PMID 37404714, 2023).
endometriosis (1 paper, 2025). The growth of functional endometrial tissue in anatomic sites outside the uterine body. "One study that assessed mRNA expression for various vitamin D‐related factors including VDR, CYP27B1 and the catabolic enzyme 24‐hydroxylase (CYP24A1) in ovarian tissues showed that women with endometriosis had higher expression of VDR, CYP27B1 and CYP24A1." (PMID 39739404, 2025).